ATP5IF1 (ATP synthase inhibitory factor subunit 1)
Description:
Endogenous F(1)F(o)-ATPase inhibitor limiting ATP depletion when the mitochondrial membrane potential falls below a threshold and the F(1)F(o)-ATP synthase starts hydrolyzing ATP to pump protons out of the mitochondrial matrix. Required to avoid the consumption of cellular ATP when the F(1)F(o)-ATP synthase enzyme acts as an ATP hydrolase. Indirectly acts as a regulator of heme synthesis in erythroid tissues: regulates heme synthesis by modulating the mitochondrial pH and redox potential, allowing FECH to efficiently catalyze the incorporation of iron into protoporphyrin IX to produce heme.
Synonyms: ATPI; ATPIF1; IP; ATPIP; MGC1167; MGC8898
Tractability: Small molecule: a structure with a bound ligand is known. PROTAC: ubiquitination databases record sites on it.
Gene: Protein-coding gene on chromosome 1 (28,236,084 to 28,246,906, forward strand). Ensembl gene ENSG00000130770.
Subcellular location: Mitochondrion
Subcellular location (Human Protein Atlas): Mitochondria
Gene Ontology:
Molecular function: angiostatin binding; ATPase binding; ATPase inhibitor activity; enzyme binding; mitochondrial proton-transporting ATP synthase complex binding; protein binding; calmodulin binding; enzyme inhibitor activity; identical protein binding
Biological process: mitochondrial depolarization; negative regulation of cardiac muscle cell apoptotic process; negative regulation of endothelial cell proliferation; negative regulation of hydrolase activity; negative regulation of mitochondrial ATP synthesis coupled proton transport; positive regulation of protein catabolic process; positive regulation of type 2 mitophagy; regulation of establishment of protein localization to mitochondrion; response to ischemia; angiogenesis; erythrocyte differentiation; generation of precursor metabolites and energy; heme biosynthetic process
Cellular component: cell surface; mitochondrion; protein-containing complex
Genetic constraint (gnomAD): Loss-of-function variants: 18 observed, 16.19 expected, observed/expected ratio (o/e) 1.11, 90% interval 0.77 to 1.64. The upper end of that interval is the gene's LOEUF score, 1.64, which puts it in group 6 of 6, group 1 being the genes least tolerant of losing a copy. Missense variants: 154 observed, 150.66 expected, observed/expected ratio (o/e) 1.02, 90% interval 0.9 to 1.17. Synonymous variants: 51 observed, 57.76 expected, observed/expected ratio (o/e) 0.88, 90% interval 0.7 to 1.12.
Homologues: Orthologues: chimpanzee ATP5IF1 (100% identical), macaque ATP5IF1 (98% identical), dog ATP5IF1 (76% identical), guinea pig ATP5IF1 (76% identical), pig ATP5IF1 (73% identical), rat Atp5if1 (58% identical), mouse Atp5if1 (52% identical), Drosophila melanogaster CG13551 (39% identical), Caenorhabditis elegans mai-2 (37% identical). Paralogues in human: MTHFS (16% identical).
Diseases named in the same sentence as ATP5IF1 in open-access papers:
ATP5IF1 is named in the same sentence as 74 diseases in open-access papers, as found by Europe PMC text mining. Sharing a sentence is not in itself a finding about the gene and the disease. The quoted sentences say what the papers report.
ischemia (9 papers, 2017 to 2026). A hypoperfusion of the BLOOD through an organ or tissue caused by a PATHOLOGIC CONSTRICTION or obstruction of its BLOOD VESSELS, or an absence of BLOOD CIRCULATION. "Neonatal cardiomyocytes activated with KynA and GPR35 linked to mitochondria appeared to interact indirectly with ATP synthase inhibitory factor subunit 1, lowering ATP loss during ischemia." (PMID 36976529, 2023).
endometrial cancer (1 paper, 2024). Primary or metastatic malignant neoplasm involving the endometrium (mucous membrane that lines the endometrial cavity). "ATP5IF1 regulates mitochondrial homeostasis and has in endometrial cancer been shown to have increased expression in tumor tissue versus normal tissue, although in tumor patients, higher levels of ATP5IF1 were associated with better overall survival." (PMID 38157275, 2024).
cancer (69 papers, 2012 to 2026). A tumor composed of atypical neoplastic, often pleomorphic cells that invade other tissues. "Here, we show that ATP5IF1 gene disruption in HeLa cells decreases colony formation in soft agar and tumor mass development in xenografts, underlining the role of IF1 in cancer." (PMID 36690622, 2023). "Except for ATP5IF1, other candidate genes included in the prognostic signature have been proven to play a vital role in cancer development." (PMID 34901000, 2021). "Collectively, these results support a model in which ATP5IF1 overexpression compromises AML cell viability in response to stress, highlighting matrix ATP consumption as a cancer cell–specific bioenergetic vulnerability, particularly relevant in the context of BCL-2-targeted chemotherapy." (PMID 40203117, 2025).
infection (9 papers, 2011 to 2026). The state of being infected such as from the introduction of a foreign agent such as serum, vaccine, antigenic substance or organism. "Previous studies have shown that ρ0 cells, which survive by maintaining mitochondrial polarization by consuming ATP, resist up-regulations in ATP5IF1 after infection with an ATP5IF1 overexpression virus." (PMID 40203117, 2025).
ATP5IF1 also shares sentences with these, for which no sentence is quoted: tumor (42 papers); breast carcinoma (15); colon carcinoma (14); cardiac hypertrophy (10); hepatocellular carcinoma (10); glioma (8); metastatic disease (7); osteosarcoma (7); colitis (5); gastric cancer (5); ovarian carcinoma (5); bladder cancer (4); cardiac disease (4); liver cancer (4); lung carcinoma (4); metabolic syndrome (4); triple-negative breast carcinoma (4); anemia (3); cardiovascular disease (3); coronary artery disease (3); diabetes (3); heart failure (3); inflammatory myopathies (3); myocardial infarction (3); non-small cell lung carcinoma (3); atherosclerosis (2); bacterial infection (2); cardiomyopathy (2); cognitive deficits (2); degenerative diseases (2).
A further 40 diseases each share a sentence with ATP5IF1 in 2 papers or fewer.